RNU6-1093P (RNA, U6 small nuclear 1093, pseudogene)
Gene: Small nuclear RNA gene on chromosome 12 (50,256,238 to 50,256,344, reverse strand). Ensembl gene ENSG00000212496.
Homologues: Orthologues: chimpanzee U6 (99% identical), macaque U6 (93% identical). Paralogues in human: RNU6-1060P (82% identical), RNU6-1131P (82% identical), RNU6-1152P (82% identical), RNU6-116P (82% identical), RNU6-1243P (82% identical), RNU6-672P (82% identical), RNU6-199P (81% identical), RNU6-429P (81% identical), RNU6-455P (81% identical), RNU6-1048P (80% identical), RNU6-1175P (80% identical), RNU6-11P (80% identical), and 1286 more.